HOTAIR (HOX transcript antisense RNA)
Diseases named in the same sentence as HOTAIR in open-access papers (continued):
Sharing a sentence is not in itself a finding about the gene and the disease.
liver cancer (continued). "Furthermore, analysis using TCGA database indicated that HOTAIR was abundantly expressed in cancer tissues of patients with liver cancer (p = 0.03) and that the expression of HOTAIR was negatively correlated with the progression free survival of patients with liver cancer." (PMID 37880710, 2023). "In conclusion, here we found that the higher expression of HOTAIR and NUAK1 and the lower expression of miR-145 promote the invasion and metastasis of liver cancer cells." (PMID 37576402, 2023). "Among these lncRNAs, HOTAIR was reported to be significantly overexpressed in HCC tissues and liver cancer cell lines." (PMID 35253323, 2022). "The HOX transcript antisense intergenic RNA (HOTAIR) is upregulated in HCC, and knockdown of HOTAIR suppressed cell proliferation and invasion in vitro as well as the growth of liver cancer cells in vivo." (PMID 36376362, 2022). "Some lncRNA, which where found to be significantly increased in other liver cancers, such as HULC (highly upregulated in liver cancer), HOTAIR and HOTTIP only showed a mild increase in FLC; while others, such as H19, showed a decrease." (PMID 29535801, 2018). "Taken together, these results suggest there is negatively correlation between the HOTAIR upregulated expression and STED2 downregulated expression in human primary liver cancer." (PMID 26172293, 2015). "Analysis of differentially expressed genes in CD13+CD133+ or negative liver cancer cell subsets in the RNA-sequencing (RNA-seq) data suggested that HOTAIR was highly expressed in LCSCs, with significant difference." (PMID 37880710, 2023). "We also tested the expression of HOTAIR in five liver cancer cell lines (HepG2, HCCLM3, MHCC-97H, SNU-387, SNU-449) and normal liver cells (MIHA) and found that the expression of HOTAIR was significantly increased in liver cancer cells compared with the normal liver cell line." (PMID 37576402, 2023). "Therefore, our study findings reveal the involvement of the HOTAIR/PRC2/miR-145-5p/NUAK1 axis in the invasion and metastasis of liver cancer cells." (PMID 37576402, 2023). "In addition, we demonstrated that HOTAIR recruits and binds to PRC2 (EZH2) to epigenetically silence miR-145-5p expression via H3K27me3 modification to promote liver cancer cell-EMT process and metastasis." (PMID 37576402, 2023). "Together our results suggest that HOTAIR may regulate the miR-145-5p /NUAK1 axis through PRC2 to induce the EMT process and enhance the invasion and metastasis of liver cancer cells." (PMID 37576402, 2023). "To determine whether HOTAIR regulates miR-145-5p expression levels by binding with PRC2, we added si-EZH2 to liver cancer cells and found that the expression of miR-145-5p increased as detected by qPCR." (PMID 37576402, 2023). "Our findings indicate that HOTAIR/miR-145-5p/NUAK1 axis acts as an EMT regulator and may be candidate prognostic biomarker and targets for new therapies in liver cancer." (PMID 37576402, 2023). "Furthermore, HOTAIR has been highlighted to interact with lysine-specific demethylase 1 (LSD1), and LSD1 expression is enhanced in liver cancer cells." (PMID 37880710, 2023). "Overexpression of HOTAIR can elevate the expression of autophagy-related 3 (ATG3) and ATG7 expression to trigger autophagy and promote HCC cell proliferation, and induce EMT of liver cancer stem cells (LCSCs) by downregulating E-cadherin." (PMID 31480503, 2019). "Given that there was negatively correlation between the expression of HOTAIR and STED2 in human primary liver cancer, we had reasons to consider whether HOTAIR influence on the SETD2 expression and its modification." (PMID 26172293, 2015). "To examine whether HOTAIR regulates EMT in liver cancer cells through NUAK1, we transfected cells with the HOTAIR overexpression plasmid (P-HOTAIR) followed by addition of the NUAK1 inhibitor HTH-01-015 and then detected EMT markers E-cadherin, N-cadherin, and Vimentin by western blot." (PMID 37576402, 2023).
liver cancer (continued). "In addition, HOTAIR also epigenetically downregulates miR-145-5p by binding to PRC2 (EZH2) to activate its target gene NUAK1, thereby promoting EMT in advanced stages of liver cancer." (PMID 37576402, 2023). "Therefore, we hypothesized that HOTAIR might act as a scaffold molecule to recruit LSD1 to the MAPK1 promoter region, further mediate ERK2 (MAPK1) expression, and ultimately increase radioresistance of liver cancer." (PMID 37880710, 2023).
colon carcinoma (39 papers, 2013 to 2024). "To complete the subgroup analysis, we analyzed the mortality of colon cancer patients, and found that patients with HOTAIR rs7958904 and rs920778 polymorphisms had greater survival rates." (PMID 32117729, 2020). "As a result, the associations between colon cancer and HOTAIR, CRNDE, and MALAT1 (top 3 predictions) were verified by the updates in the LncRNADisease database." (PMID 28963512, 2017). "Another study revealed significantly elevated expression levels of HOTAIR in colon cancer tissue compared to matched normal colon tissue adjacent to the cancer, indicating its potential as a molecular target for colon cancer treatment." (PMID 38087305, 2023). "For example, the overexpression of lncRNA HOTAIR is related to breast cancer, colon cancer, and liver cancer; the expression of miRNA miR-145 is reduced in prostate and colon cancers." (PMID 36457751, 2022). "HOTAIR is also a popular lncRNA, and a number of studies have proven that it can promote the progression of colon cancer by regulating the activity of protein-coding RNAs through an endogenous competition mechanism." (PMID 36127676, 2022). "Among them, RP5-884M6.1, RP11-742B18.1, and HOTAIR were found to be related to the occurrence of colon cancer by previous studies." (PMID 35082835, 2021). "Silencing HOTAIR can inhibit the invasion, proliferation, and migration of colon cancer LoVo cells and promote cell apoptosis by inhibiting IGF2BP2 and epithelial mesenchymal transformation." (PMID 33952279, 2021). "Propofol treatment promoted cell apoptosis and inhibited cell invasion in colon cancer cells, while the effects were reversed by HOTAIR overexpression." (PMID 31953926, 2020). "HOTAIR facilitates the migration and invasion of colon cancer cells in part via regulation of MMP-9." (PMID 33246471, 2020). "Another lncRNA, HOTAIR, was observed to be highly expressed in colon cancer tissues and correlated with tumor invasion, metastasis, tumor stage and survival time." (PMID 33246471, 2020). "RNA interference was performed to silence the expression of HOTAIR or STAT3 to explore their biological functions in colon cancer." (PMID 31953926, 2020). "First, the results showed that compared to control, colon cancer cells showed significantly higher expression of HOTAIR." (PMID 31953926, 2020). "Contrary to the reports of melanoma, retinoblastoma and colon cancer studies and expectations on the parallel expression tendencies of c-Met and HOTAIR in HCC cell lines; comparative analysis of HCC cell lines and cancer datasets shows the opposite, clearly." (PMID 32650779, 2020). "We measured HOTAIR expression levels in colon cancer and normal tissues to determine the expression pattern of specific HOTAIR polymorphisms." (PMID 32117729, 2020). "Propofol regulates the colon cancer cell apoptosis and invasion via down‐regulation of lncRNA HOTAIR." (PMID 31953926, 2020). "Here, we extended this role of HOTAIR to colon carcinoma cells conferring a more general value to the mechanism of how EZH2 gets to its genomic targets in epithelial cells undergoing EMT." (PMID 30154449, 2019). "Overall, these data provide further insights into HOTAIR function in colon carcinoma cells showing that this lncRNA (i) behaves as a mesenchymal gene in EMT and (ii) has a role in the control of Snail repressive activity." (PMID 30154449, 2019). "The inverse correlation between HOTAIR and HNF4α expression was confirmed in colon cancer cells, with HOTAIR upregulation in EMT-like SW480 cells, expressing low levels of HNF4α, and HOTAIR downregulation in MET-like HNF4α-positive SW620 cells." (PMID 30154449, 2019). "Here, the HNF4α repressive activity is extended to HOTAIR transcription both in hepatocytes and colon cancer cells." (PMID 30154449, 2019).
colon carcinoma (continued). "In conclusion, our data highlighted an involvement of HOXB13, HOXC13 and HOTAIR in proximal colon cancers pathogenesis and in lymph nodes metastasis progression, highlighting the main role of these markers in prognosis of colon cancer patients." (PMID 30541551, 2018). "To evaluate the expression level of HOTAIR, miR-125a-5p and Casp2 in colon cancer cells, we performed quantitative real-time PCR in 80 paired cancerous and adjacent noncancerous tissues of colon cancer patients." (PMID 26962687, 2016). "HOTAIR was originally found to be up-regulated in breast and colon cancers and was correlated with poor prognosis based on its interaction with PRC2 and it's epigenetic regulation of metastasis-related genes." (PMID 27147563, 2016). "For example, the lncRNA HOTAIR has been shown to be overexpressed in HCC as well as breast, pancreatic and colon cancers, and HOTAIR can serve as a tumor biomarker." (PMID 27248828, 2016). "For example, the association between colon cancer and MALAT1, HOTAIR, UCA1, KCNQ10T1, and CRNDE (ranked 2nd, 4th, 6th, 7th, 9th in the prediction results, respectively) were validated by lncRNADisease database or MNDR database." (PMID 26577439, 2015). "HOTAIR has been extensively demonstrated to correlate with poor prognosis for breast, pancreatic and colon cancer patients." (PMID 25428914, 2015). "Among lincRNAs, HOTAIR is one of the most remarkable because of its relevance to metastases in common cancers such as breast and colon cancers." (PMID 24591352, 2014). "HOTAIR can promote colon cancer progression by negatively regulating miR-34a." (PMID 38070058, 2023). "In addition, propofol attenuates metastasis of colon cancer by STAT3/HOTAIR axis through the activation of WIF-1 and the suppression of Wnt signaling." (PMID 34789263, 2021). "Moreover, STAT3 and HOTAIR were shown to independently regulate colon cancer cell apoptosis and invasion." (PMID 31953926, 2020). "We revealed that propofol could suppress the development and metastasis of colon cancer by blocking the interaction of STAT3 with HOTAIR promoter and downregulating the expression of HOTAIR, which causes the repression of Wnt signaling pathway via WIF‐1." (PMID 31953926, 2020). "Furthermore, as a key factor in Wnt signaling pathway, nuclear accumulation of β‐catenin was also obviously increased when HOTAIR was overexpressed in both colon cancer cell lines, indicating that HOTAIR enhanced the activation of Wnt pathway." (PMID 31953926, 2020). "Compared to the control group, HOTAIR knockdown group showed significantly higher apoptotic rate and less invasive cells, indicating the oncogenic function of HOTAIR in colon cancer." (PMID 31953926, 2020). "STAT3 and HOTAIR synergistically regulates the colon cancer cell apoptosis and invasion." (PMID 31953926, 2020). "Moreover, HOTAIR expression was significantly repressed in colon cancer cells on propofol treatment." (PMID 31953926, 2020). "Overall, these data indicate that HOTAIR is directly repressed by HNF4α, both in the stable maintenance of epithelial identity and during MET transdifferentiation, whereas HOTAIR gene repression is released by HNF4α impairment, both in hepatocytes and in colon carcinoma cells." (PMID 30154449, 2019). "Specifically, the aberrant expression of the HOXB13, HOXC13 and HOTAIR in proximal colon cancers could add an important dowel in understanding molecular mechanisms related to tumor pathogenesis in this location." (PMID 30541551, 2018).
colon carcinoma (continued). "Furthermore, the knockdown of HOTAIR in irradiated CRC cells led to a decreased expression of metalloproteinase 2 (MMP2) and metalloproteinase 9 (MMP9) suggesting a role of HOTAIR in influencing the invasion and migration of colon cancer cells after irradiation." (PMID 38887279, 2024). "In addition, HOTAIR can accelerate colon cancer development by down-regulating miRNA-34a." (PMID 32117729, 2020). "In colon cancer, suppression of the lncRNA HOTAIR was found to downregulate the expression of IGF2BP2; HOTAIR can inhibit EMT, proliferation, cell cycle, metastasis, and invasion and facilitate cell apoptosis." (PMID 37965577, 2023). "In turn, elevated levels of lncRNA HOX Transcript Antisense RNA (HOTAIR) were also found in CRC tissues from patients and in colon cancer cell lines." (PMID 35922756, 2022). "HNF4α, a master factor of MET and inducer of epithelial differentiation, was found to directly repress HOTAIR transcription thus antagonizing the EMT of both hepatocytes and colon cancer cells." (PMID 30154449, 2019). "Several studies showed that HOTAIR knockdown can repress TGF-β1, which induces EMT and reduces the colony-forming ability of colon cancer cells." (PMID 29299179, 2017). "Interestingly, when we silenced both HOTAIR and STAT3 in colon cancer cells, the apoptotic rate was higher than knockdown on either HOTAIR or STAT3 alone." (PMID 31953926, 2020). "Further analysis on the EMT‐related markers showed that HOTAIR overexpression inhibited E‐cadherin expression and increased N‐cadherin level, indicating that HOTAIR could promote EMT in colon cancer cell lines." (PMID 31953926, 2020). "Compared with the non-stem cell subpopulations, the colon cancer stem cell subpopulation (CD133 (+)/CD44 (+)) possesses higher levels of HOTAIR, suggesting that HOTAIR aids in carcinogenesis via the acquisition of stemness." (PMID 29299179, 2017). "Taken together, our results revealed that propofol could promote apoptosis and inhibit invasion, mainly through its inhibition on STAT3 and HOTAIR to deactivate Wnt signaling pathway by increasing WIF‐1 expression levels, which might serve as a therapeutic role for colon cancer." (PMID 31953926, 2020). "The functions of lncRNA AWPPH in proliferation of colon cancer cells were regulated by targeting GLUT-1; LncRNA CCAT1 promotes autophagy of liver cancer cells via regulating ATG7 by sponging miR-181; LncRNA HOTAIR promotes colon cancer progress by targeting miR-34a." (PMID 31900207, 2020). "In addition, they observed elevated HOTAIR levels in a colon cancer stem cell subpopulation compared with a non-stem cell subpopulation, indicating that HOTAIR might be required for EMT and stemness maintenance." (PMID 27608009, 2016).
non-small cell lung carcinoma (37 papers, 2013 to 2026). A group of at least three distinct histological types of lung cancer, including non-small cell squamous cell carcinoma, adenocarcinoma, and large cell carcinoma. "lncRNAs like MALAT1 and HOTAIR have been associated with aggressive tumor behavior and poor patient outcomes in non-small-cell lung cancer (NSCLC)." (PMID 39452836, 2024). "A higher HOTAIR expression is also strongly associated with cisplatin resistance in non-small cell lung cancer (NSCLC) patients." (PMID 32397382, 2020). "Previously, it has been shown that increased HOTAIR expression promoted tumor sphere formation in non-small cell lung cancer cells via upregulation of the stem cell-associated markers, including Sox2, Nanog, Oct3/4, c-Myc, β-catenin and Klf4." (PMID 29228709, 2017). "Recently, it was reported that HOTAIR expression in non-small cell lung cancer (NSCLC) was dramatically higher than that in adjacent tissues and that high HOTAIR expression was associated with shortened overall patient survival." (PMID 36100611, 2022). "LncRNA HOX antisense intergenic RNA (HOTAIR), as an oncogene in non-small cell lung cancer (NSCLC), is one of the key determinants of tumor progression." (PMID 35176085, 2022). "Altogether, our data indicated that HOTAIR regulates cell cycle progression through epigenetic regulation of EZH2/H3K27 in non-small cell lung cancer cells." (PMID 34405017, 2021). "Another example proposed that the knockdown of HOTAIR inhibits ULK1 phosphorylation-mediated autophagy to refrain drug resistance of non-small cell lung cancer cells." (PMID 32760216, 2020). "A lot of lncRNAs, including MALAT1, HOTAIR, CCAT2, and AK126698, were found to be associated with non-small cell lung cancer (NSCLC) progression, metastasis, and invasion." (PMID 32607061, 2020). "In non-small cell lung cancer (NSLC) patients, high HOTAIR expression is associated with drug resistance." (PMID 31072041, 2019). "Targeting miR-34a-5p and HOTAIR may be a viable therapeutic approach to regulate non-small cell lung cancer development and metastasis, as the combination of BBR and gefitinib intensifies the inhibition of this pathway." (PMID 39896297, 2025). "In addition, HOTAIR mediates cisplatin (DDP)-resistant non-small cell lung cancer by regulating the Wnt signaling pathway; however, the role of HOTAIR in DDP resistance in NPC is not clearly understood." (PMID 35227173, 2022). "Targeting HOTAIR may be a novel therapeutic strategy for treating gefitinib-resistance in non-small cell lung cancer." (PMID 34405017, 2021). "Importantly, HOTAIR expression was upregulated in cancer tissue samples from patients with breast, pancreatic, liver, gastric, and non-small cell lung cancers, and elevated HOTAIR expression was even more pronounced in metastatic tissue." (PMID 32117729, 2020). "HOX transcript antisense intergenic RNA (HOTAIR) is also correlated with the tumor stage and poor prognosis of non-small-cell lung cancer; the down-regulation of HOTAIR inhibits the invasion and metastasis of non-small-cell lung cancer cells through the down-regulation of HOXA5." (PMID 27527868, 2016). "Moreover the expression of HOTAIR and Col-1 was concurrently up-regulated in human non-small cell lung cancer." (PMID 23668363, 2013). "HOTAIR exhibits significantly higher expression in the tumor tissue than the adjacent non-tumor tissue in patients with small cell lung cancer (SCLC) and non-small cell lung cancer (NSCLC)." (PMID 25491133, 2014). "Furthermore, HOTAIR’s inhibition of HOTAIRM1 through the miR-498/ABCE1 axis impedes glycolytic metabolism and the progression of tumors in non-small-cell lung cancer cells." (PMID 40723840, 2025). "HOTAIR is an oncogenic lncRNA and a negative prognostic factor for several types of cancer, such as non-small cell lung cancer (NSCLC), breast, cervical, and endometrial cancer." (PMID 33673376, 2021).
non-small cell lung carcinoma (continued). "We analyzed the gene expression data from GEO (GEO series accession No. GSE19188), and the results show that HOTAIR is aberrantly upregulated in 91 non-small cell lung cancer tissues compared with 65 adjacent normal lung tissues." (PMID 33102210, 2020).